STAT3 (signal transducer and activator of transcription 3)
Diseases named in the same sentence as STAT3 in open-access papers (continued):
Sharing a sentence is not in itself a finding about the gene and the disease.
breast cancer (continued). "Thus, blockade of STAT3 in migratory cDC1s may be a novel means to overcome tumor immunosuppression and improve the efficacy of immunotherapies in human breast cancer." (PMID 31947933, 2020). "Intriguingly, STAT3, AKT, integrin β1 and Bcl-3 are linked to the activities of CSCs or embryonal stem cells, while CAF-CM and IL-6 are able to upregulate the RNA level of the CSC marker ALDH1A1 and while IL-6 has the potential to increase CSC activity in breast cancer cells." (PMID 33228022, 2020). "Taken together, these results revealed that inactivation of STAT3 was a novel mechanism with treatment of PP and PL, suggesting that combination application of natural alkaloids may be a potential strategy for prevention and therapy of breast cancer." (PMID 31948057, 2020). "In addition, our evidence also indicated that G-CSF could cooperate with other CAA-secreted factors, such as IL-6 and GM-CSF, to activate Stat3 signaling and promote breast cancer cell migration." (PMID 32242230, 2020). "BPMB could selectively inhibit proliferation in constitutively-activated STAT3 breast cancer cells." (PMID 32872659, 2020). "In addition, immunohistochemistry (IHC) analysis showed that, although extremely low in normal mammary tissues, both G-CSF and p-Stat3 levels were high in breast cancer tissues, with elevated G-CSF level in adipocytes correlating well with strong p-Stat3 signal in cancer cells." (PMID 32242230, 2020). "Leptin signaling may lead to STAT3 activation of HIF-1α in breast cancer and therefore may also drive CPT1 expression resulting in nuclear regulation of energy generation; a critical activity for cellular survival particularly in unfavourable hypoxic environments." (PMID 32331320, 2020). "Additionally, the discovery of small molecular compounds interfering with the cooperation of HIF‐1α/STAT3 may gain more insights to the clinical treatment for breast cancer." (PMID 32065498, 2020). "Also, the immunosuppressive activity and differentiation of MDSCs isolated from breast cancer patients were examined before and after targeting the STAT3 transcription factor using siRNA in MDSCs along with simultaneous activation of the TLR7/TLR8 signaling using a specific agonist." (PMID 33679700, 2020). "could restrain breast cancer metastasis by blockage Stat3/MMP pathway in vivo and in vitro." (PMID 31649548, 2019). "Notably, curcumin has demonstrated potent anti-STAT3 activity through STAT3 cysteine modification that prevents phosphorylation and it has been found to inhibit proliferation breast cancer and esophageal squamous cell carcinoma, with the latter being associated with significant decreases in IL-6." (PMID 31842362, 2019). "To this end, we examined the METABRIC breast cancer dataset for the expression of a signature composed of the genes belonging to the IL-6 or the WNT non-canonical pathways characterized by in vivo binding of both STAT3 and SP1, as identified above, denominated the SP1-S3 signature." (PMID 30654518, 2019). "may be a promising agent in breast cancer chemotherapy by targeting Stat3 signaling pathway." (PMID 31649548, 2019). "As our and other previous studies have evidenced that GPER triggers a specific gene signature in breast cancer cells toward relevant biological effects, we then sought to investigate whether STAT3 may contribute to gene expression changes mediated by GPER in MDA-MB 231 cells." (PMID 30728047, 2019). "However, high STAT3 protein expression levels predicted a better prognosis for breast cancer." (PMID 31557897, 2019). "Therefore, CAPE-pNO2 against the growth and metastasis of breast cancer might be via restraining MMP-2, MMP-9, and VEGFA expression, and these proteins were associated with the EGFR/STAT3/Akt signaling pathway." (PMID 31214503, 2019).
breast cancer (continued). "Interestingly, LIF receptor/STAT3 signaling is proved to be a dormancy phenotype to disseminated breast cancer cells, and inactivation of JAK/STAT pathway might contribute to disease progression and metastasis." (PMID 31649548, 2019). "Moreover, the genomic signature of TNBC conferring STAT3 activation could be a predictive tool for poor prognosis in breast cancer patients." (PMID 31324052, 2019). "In addition, the precise mechanism by which IL-32θ reduces the effects of macrophage on breast cancer progression was addressed based on previous studies detailing that IL-32θ interacted directly with PKCδ to subsequently decrease STAT3 or NF-κB signaling in PMA-activated THP-1 cells." (PMID 31126309, 2019). "Therefore, targeting Stat3 might be still an attractive approach for breast cancer and lung metastasis therapy." (PMID 31649548, 2019). "Thus, we hypothesize that various upstream signaling pathways of STAT3 contribute to distinct prognosis in different breast cancer subtypes." (PMID 29560131, 2018). "The researches in breast cancer may provide some references for STAT3 regulation by PTPN9 in HCC." (PMID 29558404, 2018). "Furthermore, the IL-6/STAT3 signaling pathway could be a promising candidate target in developing novel therapeutic strategies to eliminate e-MDSCs and improve breast cancer prognosis." (PMID 30083161, 2018). "The possible TAMs-modulated drug resistance mechanism involved may be associated with elevation of bcl-2 gene expression and up-regulation of STAT3 signaling in tumor cells, forming IL-10/STAT3/bcl-2 signaling axis accounting for chemoresistance of breast cancer." (PMID 30175384, 2018). "Therefore, we analyzed whether the pooled insignificant HR is interconnected with different biomarkers (STAT3 and p-STAT3) of breast cancer." (PMID 29560131, 2018). "Another study reported a loss of TC-PTP in triple-negative primary breast cancer, and TC-PTP deficiency in human breast cancer cell lines resulted in increased cell proliferation in vitro and xenograft in vivo via reduced SFK (Src family protein tyrosine kinases) and STAT3 signaling." (PMID 30208623, 2018). "Moreover, the IL-6/STAT3 signaling pathway might be a promising candidate target in developing novel therapeutic strategies to eliminate e-MDSCs and improve breast cancer prognosis." (PMID 30083161, 2018). "However, in breast cancer, IL-6 promotes the activities of STAT3." (PMID 30325954, 2018). "In addition, constitutive Stat3 also has an important role in controlling cell migration and invasion, suggesting that targeting Stat3 might be a potentially important new form of breast cancer therapy." (PMID 29423083, 2018). "However, the unbiased gene co-expression analysis did not detect the association between P4HA1 and the STAT3 pathway or gene signature in human breast cancer tissues." (PMID 30367042, 2018). "Therefore, to assess the tumorigenic or tumor suppressor role of STAT3 in breast cancer, many previous studies have demonstrated that the protein expression was significantly up-regulated in breast cancer tissues compared with their matched normal breast tissues." (PMID 29423040, 2018). "Notably, on one side, STAT3 is aberrantly active in many breast cancers, on the other, at the physiological level, it is the main mediator of epithelial cell death during post-lactation mammary-gland involution, thus strongly suggesting that its biological functions are highly context-specific." (PMID 30231553, 2018). "A previous report suggests that STAT3 could be downmodulated by C12-HSL in breast carcinoma." (PMID 29854771, 2018). "For instance, reversion-inducing cysteine-rich protein with kazal motifs (RECK) inhibits STAT3 activity by binding with β1-integrin, IL-6RA, glycoprotein 130 (gp130), and urokinase receptor (uPAR) in the membrane, resulting in remarkable STAT3 inhibition in breast cancer cells." (PMID 28978186, 2017).
breast cancer (continued). "Finally, to assess whether OncoLead-inferred target inhibitors are conserved across different cellular contexts, we tested the breast cancer specific prediction for STAT3 inhibitors in human glioblastoma cells." (PMID 29023443, 2017). "Furthermore, in a murine breast cancer model, a cancer vaccine therapy employing the systemic delivery of a tumor-targeting Salmonella-based STAT3 shRNA increased the proliferation and granzyme B levels of intratumoral CD4+ and CD8+ T cells, which favored the destruction of malignant cells." (PMID 29115974, 2017). "Therefore, STAT3 may be a promising therapeutic target for overcoming drug resistance in breast cancer." (PMID 28864784, 2017). "Moreover, STAT3 inhibition represses CSC traits in HER2-positive breast cancers." (PMID 28270211, 2017). "However, inhibition of STAT3 abrogates Ras-induced IL-11 transcription in breast cancer." (PMID 28856117, 2017). "Similarly, STAT3 expression was meaningfully decreased in the last stage of breast cancer." (PMID 29299026, 2017). "Moreover, mitochondrial Stat3-mediated accumulation of ROS promoted breast cancer growth." (PMID 29133922, 2017). "Indeed, we could identify human breast tumours that coordinately increase STAT1- and STAT3-driven transcriptional responses in human breast cancers." (PMID 28276425, 2017). "In this study, we confirmed that acquired lapatinib-resistant HER2-positive breast cancer cells had elevated IL-6, and that elevated IL-6 maintained the stemness population and property within these resistant cells through the activation of signal transducer and activator of transcription 3 (STAT3)." (PMID 27694691, 2016). "Therefore, IL-1β in the tumor microenvironment and tumor cell TG2 and IL-6/STAT3 signaling pathway may be potential targets for combating recurrent and therapy-resistant luminal-type breast cancer." (PMID 27609180, 2016). "Indeed, phosphorylated STAT3 is expressed in about 40% of all breast cancers, and its constitutive phosphorylation was associated with trastuzumab resistance in HER2-positive breast cancers." (PMID 27248826, 2016). "However, recent studies demonstrated that STAT3-targeted inhibitor could restrain tumor development in various solid tumor models including breast cancer, melanoma and ovarian cancer." (PMID 26959884, 2016). "Our study may have a significant impact on determining the therapeutic efficacy of novel STAT3/5 small molecule inhibitors such as SH-4-54 aimed at treating breast cancer and other aggressive cancers in which the ying-yang effects of STAT proteins play a central role, such as leukemias." (PMID 27513743, 2016). "Furthermore, inhibition of STAT3 activation or depletion of survivin also sensitized HER2-positive breast cancer cells to irradiation, suggesting that the HER2-STAT3-survivin axis is a key pathway in radiotherapy resistance of HER2-positive breast cancer cells." (PMID 26755645, 2016). "Mechanistically, STAT3-mediated upregulation of hTERT expression may be the result of the following biological factors: leptin induction in breast cancer and HCC cells, miR-21 expression in glioblastoma cells, and core protein of hepatitis C virus (HCVc) in HCC cells." (PMID 27548225, 2016). "Thus, inhibition of STAT3 activity may specifically promote further development of breast cancer under certain conditions." (PMID 26768588, 2016). "Therefore, Stat3 has a crucial role in the pathogenesis and radiation resistance of breast cancer." (PMID 27815936, 2016). "STAT3 activation of target genes such as TGF-β1 and hypoxia inducible factor- (HIF-) 1α has been linked to EMT reprograming and several recent studies have shown that TAM-secreted IL-6, EGF, or MFGE-8 can activate STAT3 signaling in CSCs of breast cancer, HCC, or colon cancer." (PMID 26980947, 2016). "However, the apparent paradox that STAT3 is required for cell death in normal mammary gland, but is associated with breast cancer cell survival, has not been resolved." (PMID 27711075, 2016).
breast cancer (continued). "In addition, a report indicated that STAT3 could promote epithelial to mesenchymal transition in breast cancer cells." (PMID 27833137, 2016). "Targeting Stat3 and NF-κB may also be useful to treat breast cancer." (PMID 26169986, 2015). "In this study, we revealed that STAT3 inhibition significantly increased the antitumor effect of trastuzumab on EGFRvIII+HER2+ breast cancers, implicating that STAT3 inhibitors might be used to increase the antitumor effect of trastuzumab on EGFRvIII+HER2+ breast cancers.." (PMID 26474285, 2015). "Therefore, we considered whether the association between GRN expression and a STAT3-dependent gene expression signature would be more pronounced in breast cancers displaying STAT3 tyrosine phosphorylation." (PMID 26000098, 2015). "Finally, the oxidation of conserved STAT3 cysteines was shown to negatively modulate its activity on a subset of target genes, reducing proliferation but enhancing resistance to oxidative stress in breast cancer cells." (PMID 26106584, 2015). "According to the efficacy of CH12 and the inhibition effect against ERK, AKT and Jak1/STAT3 pathway in EGFRvIII+HER2+ breast cancers, we wondered whether the combination of trastuzumab with CH12 could reverse trastuzumab resistance in EGFRvIII+HER2+ breast cancer." (PMID 26474285, 2015). "Finally, we investigated whether STAT3 down-regulation is sufficient to inhibit basal-like breast cancer cell viability." (PMID 25699542, 2015). "Additionally, downregulation of miR-200 and let-7 via STAT3 can induce the EMT phenomenon in breast cancer; conversely, inactivation of STAT3 or re-expression of both miRNAs proved sufficient to induce mesenchymal-to-epithelial transition (MET) in mesenchymal breast cancer." (PMID 26631279, 2015). "However, proteins that functionally interact with STAT3 in breast cancer have yet to be defined." (PMID 26000098, 2015). "Furthermore, conditioned medium from senescent MSCs could activate STAT3, the main downstream transcription factor of IL-6, in breast cancer cells, and the activation could be blocked by an IL-6-neutralizing antibody." (PMID 25419563, 2014). "Their use in immunoblotting studies revealed for the first time that levels of Stat3β protein in breast cancer cell lines positively correlated with overall pStat3 levels, suggesting that Stat3β may contribute to constitutive Stat3 activation in this tumor system." (PMID 25268166, 2014). "Consequently, STAT3 may be considered a promising target in the field of cancer therapy and, also, for stem-cell-directed therapy in some breast cancer subtypes." (PMID 25026286, 2014). "In addition to breast cancer, STAT3 stays constitutively activated in other types of cancers." (PMID 24743778, 2014). "Altogether these findings indicate that impairment of STAT3 activity in the context of post-surgical inflammation may result in the targeting of breast cancer cells with stem-like phenotypes, eventually leading to successful suppression of cancer local relapse." (PMID 25026286, 2014). "Thus, in breast cancer, it has been reported that STAT3 upregulates the expression and function of β-catenin whilst in oesophageal and some haematological malignancies, β-catenin appears to upregulate the expression of STAT3." (PMID 25348333, 2014). "However, whether STAT3 inhibition can improve our success in treating breast cancer remains to be studied in future studies." (PMID 24376586, 2013). "Consequently, high expression levels of CD44 may lead to a constitutive activation of STAT3 signaling in basal-type breast cancer." (PMID 23326564, 2013). "According to our findings, Syndecan-1 silencing in triple-negative MDA-MB-231 breast cancer cells inhibited proinflammatory signaling via downregulation of relevant receptors and ligands (IL-6/IL6-R/CCL20), which was linked to reduced constitutive activation of NFkB and STAT3." (PMID 24392029, 2013).
breast cancer (continued). "Constitutively activated STAT3 can directly contribute to tumorigenesis, invasion and metastasis, and it has been shown that elevated tyrosine-phosphorylated STAT3 (p-STAT3) correlates with incomplete response to neoadjuvant chemotherapy in stage II breast cancers." (PMID 23938089, 2013). "However, there is limited data showing SHP-1 substrates other than p-STAT3 in breast cancer cells." (PMID 23938089, 2013). "Importantly, we find that STAT3 in the JAK-STAT signaling pathway may partially mediate the resistance of breast cancer stem cells to tamoxifen." (PMID 23554768, 2012). "In support of this hypothesis, we have previously shown that the rapid effects of PR mediate Stat3 transcriptional activation in breast tumors and that activated Stat3 in turn participates in the transcriptional mechanisms of PR that drive mammary tumor growth." (PMID 22583478, 2012). "It was concluded that HC is a potent agent in the inhibition of STAT3 with more favorable pharmacological activity than curcumin, and HC may have translational potential as an effective cancer therapeutic or preventive agent for human breast carcinoma." (PMID 22179587, 2012). "It was concluded that HC is a potent agent in inhibiting the phosphorylation of STAT3 with a more favorable pharmacological activity than curcumin, and HC might have translational potential as an effective drug or preventive agent for human breast carcinoma." (PMID 22179587, 2012). "In this regard, STAT3 might be an attractive therapeutic target in BM from breast cancer." (PMID 22567347, 2011). "Hence, specifically targeting STAT3 in ErbB2-overexpressing breast cancer cells that contain activated STAT3 may inhibit ErbB2-mediated malignant phenotypes." (PMID 27713313, 2010). "In order to determine whether caspase-dependent cleavage of human STAT3α occurs in breast cancer, we carried out immunoblot analysis of 1 normal breast line and 7 breast cancer cell lines with varying levels of tyrosine phosphorylated STAT3 (PY 705 STAT3 panel)." (PMID 17295906, 2007). "The additional cleavage observed in breast cancer cell lines close to a consensus caspase 3 cleavage site to generate a 25 kDa amino terminal fragment, could be a mechanism to decrease the level of constitutively active STAT3 in these cells." (PMID 17295906, 2007). "Interestingly, blocking Stat3 activation enhanced this effect in mammary tumor cells." (PMID 17925034, 2007). "Previous studies have identified several FOSL1‐mediated stemness inducers such as IL‐6/STAT3 and SNAI3 in breast cancer, suggesting that drug resistance is induced by the FOSL1‐IL‐6/STAT3‐stemness axis." (PMID 41556041, 2026). "Pexidartinib inhibited macrophage activity, suppressed STAT3 phosphorylation, reduced ARG1 expression, and increased lymphocyte viability, thereby enhancing the antitumor efficacy of palbociclib in HR + /HER2- breast cancer." (PMID 41986650, 2026). "In this work, we developed an in vitro assay to trigger dormancy in HER2-amplified human breast cancer cells and studied the induction of CSC features, as well as the function of JAK1 and STAT3, components of the IL-6–STAT3 axis." (PMID 40430044, 2025). "A recent study also highlighted the importance of STAT3 signaling activated by TAM-derived IL-6 in CSC enrichment and tumor growth in breast cancer." (PMID 40083697, 2025). "In MCF-7 breast cancer cells, orientin inhibited migration and invasion by suppressing the PKCα/ERK/AP-1/STAT3 signaling axis, leading to decreased expression of matrix metalloproteinase-9 (MMP-9) and interleukin-8 (IL-8)." (PMID 40725115, 2025). "For instance, STAT3 and STAT5 exhibit reciprocal and sometimes opposing effects in breast cancer on gene expression and cellular behavior." (PMID 41301421, 2025). "This suggests that Osthole possesses the ability to inhibit both the proliferation and metastatic capabilities of breast cancer cells, primarily through the suppression of the JAK2/STAT3 signaling cascade." (PMID 40978029, 2025).